FLT1 (fms related receptor tyrosine kinase 1)
Diseases named in the same sentence as FLT1 in open-access papers (continued):
Sharing a sentence is not in itself a finding about the gene and the disease.
colon carcinoma (34 papers, 2006 to 2026). "Methylation of the FLT1 promoter was also found to be significantly higher in the tumor tissues of stomach cancer, colon cancer, hepatocellular carcinoma, and renal cancer, in comparison with normal tissues." (PMID 32041578, 2020). "FLT1 methylation has been observed in lung, stomach, and colon cancer cells." (PMID 26380584, 2015). "Human VEGFR expression profile varied widely depending on tumor types with particularly high levels of human FLT1/VEGFR1 transcripts in colon cancers and non small cell lung carcinomas, and upper levels of human KDR/VEGFR2 transcripts in non small cell lung carcinomas." (PMID 24625025, 2014). "FLT1, a member of the VEGF receptor (VEGFR) family, along with ANGPT2 and PGF, plays a role in vascular development and contributes to colon cancer progression." (PMID 41441010, 2025). "In our study, we similarly observed significantly reduced expression of ANGPT2 in both right- and left-sided colon cancers, with FLT1 and PGF showing even lower expression in left-sided colon cancer." (PMID 41441010, 2025). "Other cancer related genes include the TFF3 gene, which was shown to activate STAT3, (an oncogene) signaling in human colonic cancers and the VEGF receptor FLT1 gene." (PMID 19458770, 2007). "Although these genes are found to be overexpressed in several malignant tumours, including gastric and colon cancers, it remains unclear whether the products of FGF9, FLT1 and KLF5 are overexpressed in colorectal intramucosal adenocarcinoma." (PMID 28197804, 2017). "In the pathogenesis of metastatic CRC, abundant miR-200c could be detected in liver metastasis tissues, and overexpression of miR-200c in colon cancer cell lines led to a reduced expression of its target genes ZEB1, ETS1 and FLT1, and EMT markers (E-cadherin and vimentin)." (PMID 26064956, 2015).
hepatocellular carcinoma (32 papers, 2008 to 2025). A malignant tumor that arises from hepatocytes. "The high expression of FLT1 coupled with low expression of KDR in endothelial cells is also observed in gastric cancer (GC) and hepatocellular carcinoma (HCC), where the expression level of PGF inversely correlates with patient overall survival rates." (PMID 39628692, 2024). "External validation confirmed positive correlations for FAP and angiogenesis receptors FLT1, KDR, and KIT as well as HIF1A and ETS1 in hepatocellular carcinoma but also in metastatic prostate cancer (Dream Team cohort)." (PMID 36672341, 2023). "FLT1 can bind to VEGFR-A, VEGFR-B and FGF2 and play an important role in promoting endothelial cell proliferation, survival and angiogenesis in Hepatocellular Carcinoma, Non-Small Cell Lung Cancer and Esophageal Cancer 26-29." (PMID 31632486, 2019). "The results of target prediction showed that PDGFRA, FLT1, PIK3CD and MET might be the main targets of compound 15 against hepatocellular carcinoma." (PMID 41023382, 2025). "In hepatocellular carcinoma (HCC), circ-CCT3 sponges miR-378a-3p restoring fms-related receptor tyrosine kinase 1 (FLT1) expression and accelerating HCC progression." (PMID 41153715, 2025). "PPARβ/δ ligands induce VEGF in bladder cancer cells, humanbreast (T47D, MCF7), and prostate (LNCaP, PNT1A) cancer cell lines, along withits receptor flt-1, but not (HT29, colon; HCT116, colon; LS-174T, colon; HepG2,hepatoma; and HuH7, hepatoma) cell lines." (PMID 18382612, 2008).
diabetes (30 papers, 2011 to 2026). "Moreover, we found 20% and 8% lower concentrations of Flt-1, a soluble vascular endothelial growth factor receptor, at 10 and 5 years before diagnosis, respectively, after which it normalised to that of the non-diabetes group." (PMID 39078488, 2024). "GFAP, Flt1, 8-OHdG and TNF-ɑ immunoreactivity were increased, and ɑ-SMA, PEDF and SOD3 immunoreactivity were decreased in the diabetic retina." (PMID 35015779, 2022). "We found that Flt-1, sICAM-1 and Tie-2 increased towards the time of diabetes diagnosis, although the per-year effects were not significant for sICAM-1 and Tie-2 after FDR adjustment." (PMID 39078488, 2024). "Expression of KDR (Flk-1, VEGFR-2), the major receptor mediating the proangiogenic VEGF action, was higher in db/db cells, and not modified by rosiglitazone, while Flt-1 (VEGFR-1) level was affected neither by diabetes nor by rosiglitazone." (PMID 25361524, 2014). "Diabetes did not alter the mRNA expression of the VEGF receptors FLT1 and KDR." (PMID 23878504, 2013). "The VEGF receptors FLT1 and KDR significantly decreased after 12 weeks in the control and diabetic rats (p<0.02), which is most likely due to age effects, not diabetes." (PMID 23878504, 2013).
gastric cancer (24 papers, 2007 to 2024). A primary or metastatic malignant neoplasm involving the stomach. "C11_VWF were characterized by co‐expressing marker genes of fibroblasts (COL1A1, FAP, VIM, ACTA2) and endothelial cells (VWF, PECAM1, CLDN5, FLT1, RAMP2), which resembled a subgroup of cells undergoing an EMT transition in gastric cancer." (PMID 38115703, 2023).
lung carcinoma (22 papers, 2008 to 2024). "VEGF level in MPM patients is a biomarker for unfavorable prognosis, and lung cancer tumors expressing FLT1 have been associated with poor prognosis." (PMID 33916178, 2021). "In particular, FLT1 predicted by DriverMP has high sequence similarity to the KDR gene associated with lung cancer in CGC, and related studies showed that tumors expressing both FLT1 and KDR may have a greater malignant potential and a poorer prognosis." (PMID 38091511, 2022). "FLT1/VEGFR1 and KDR/VEGFR2 were also confirmed as direct targets of miR-200 in lung cancer cells, modulating invasion, metastasis, and radiosensitivity." (PMID 38766528, 2024). "The gene expression level of VEGFA, PGF, and their receptors FLT1 and KDR as well as MMP-2 and the inhibitors TIMP-1 and TIMP-2 was higher in samples from lung cancer resections compared to pneumothorax and transplant biopsy samples." (PMID 22593690, 2012). "Despite the high gene expression levels of VEGFA, PGF, FLT1, KDR, MMP-2, TIMP-1, and TIMP-2, only KDR and TIMP-1 were high at the protein level in the lung cancer resections." (PMID 22593690, 2012). "Angiogenesis in lung cancer tissues not only depends on the amount of VEGF secretion, but also requires a series of signal transduction events downstream of receptor binding, namely FLT-1 and KDR." (PMID 36870024, 2023). "The gene expression level of VEGFA, PGF, and their receptors FLT1 and KDR as well as MMP-2 and the inhibitors TIMP-1 and TIMP-2 was significantly higher in lung cancer specimens compared to pneumothorax samples and biopsies from lung transplant patients (P < 0.001)." (PMID 22593690, 2012). "First, we determined whether troglitazone affects the expression of VEGF-A and its receptors, fms-like tyrosine kinase (FLT-1/VEGFR1), kinase insert domain receptor 1 (KDR/VEGFR2), and neuropilin-1 (NRP-1) in the human lung cancer cell lines, RERF-LC-AI, SK-MES-1, PC-14, and A549." (PMID 20214829, 2010).
renal cell carcinoma (22 papers, 2011 to 2025). "Besides, RACK1 can modulate PI3K/Akt signaling or activates Akt to propel cell proliferation and invasion/metastasis in VEGF/Flt1-mediated endothelial cells, mouse hepatocarcinoma cells, renal cell carcinoma, and some other cancers." (PMID 27170279, 2016).
Obesity (20 papers, 2014 to 2025). Accumulation of substantial excess body fat. "In this study, increased VEGFA bioavailability induced by deletion of the VEGFA receptors VEGFR1, encoded by Flt1 and Nrp1, protected mice from diet-induced obesity." (PMID 34299378, 2021). "The only two genes upregulated across all transcriptome-wide PE analyses to date (microarray, RNA-Seq and PAS-Seq) are NRIP1 (RIP140), a transcriptional co-regulator linked to metabolic syndromes associated with obesity, and Flt1." (PMID 28939845, 2017). "FLT1 exhibited a causal relationship with obesity (OR: 0.939, 95% CI: 0.901–0.978, P = 0.002), GAP43 showed a causal relationship with obesity (OR: 0.897, 95% CI: 0.806–0.998, P = 0.046), and SLITRK1 was causally linked to obesity (OR: 0.855, 95% CI: 0.736–0.994, P = 0.041)." (PMID 40372036, 2025). "By analyzing genes associated with SNPs causally linked to obesity, gut microbiota, and metabolites, we found that FLT1, GAP43, and SLITRK1 proteins potentially reduce the risk of obesity." (PMID 40372036, 2025). "The study investigated the causal relationship between three plasma proteins (FLT1, GAP43, and SLITRK1) and obesity, finding that they have a protective effect against obesity risk." (PMID 40372036, 2025). "The findings of the study revealed that three plasma proteins (FLT1, GAP43, and SLITRK1) were significantly associated with the risk of obesity and showed a causal relationship." (PMID 40372036, 2025). "In summary, the study identified three plasma proteins, FLT1, GAP43, and SLITRK1, as having a protective effect against obesity risk." (PMID 40372036, 2025). "Fms-related receptor tyrosine kinase 1 (FLT1), growth-associated protein 43 (GAP43), and SLIT and NTRK-like family member 1 (SLITRK1) plasma proteins had protective effects against obesity." (PMID 40372036, 2025). "It identified three plasma proteins (FLT1, GAP43, and SLITRK1) that were significantly associated with obesity and showed a causal relationship." (PMID 40372036, 2025). "We observed significant upregulation of genes such as Cyp11a1, Fdx1, Flt1, Gm2a, and S100a6 in the G05 subpopulation under the influence of obesity." (PMID 38956667, 2024). "High VEGF-A signaling by deletion of NRP1 and FLT1 increases zipper-like junctions to make lacteals tighter, lipid uptake lower, which protects against obesity." (PMID 36506056, 2022). "The deletion of the Nrp1 and Flt1 genes renders mice resistant to diet-induced obesity because of less lacteal CM uptake." (PMID 35205322, 2022). "Flt-1 (VEGFR1) is thought to play a role in obesity-related tumour progression that is unrelated to the angiogenic process." (PMID 34822426, 2021). "FLT1, GAP43, and SLITRK1 remained significant under the MR hypothesis and were identified as having a cause-and-effect relationship with obesity according to the IVW method." (PMID 40372036, 2025).
ovarian carcinoma (19 papers, 2009 to 2023). A malignant neoplasm originating from the surface ovarian epithelium. "SMARCA4 mutation was associated with sensitivity to four FLT1 (VEGFR1) inhibitors in ovarian cancer cells, including axitinib, foretinib, pazopanib and sorafenib." (PMID 36180906, 2022). "For instance, SMARCA4, a subunit of the SWI/SNF chromatin remodeling complex, and FLT1 (VEGFR1) were identified as a CSL interaction in ovarian cancer cells." (PMID 36180906, 2022). "The protein expression levels of VEGF and its receptors, Flt-1 and KDR/Flk-1, were detected in 48 cases of ovarian cancer using the streptavidin-biotin complex (SABC) immunohistochemical method, and tumor MVD was evaluated using F8 factor (FVIII-RA)." (PMID 23946799, 2013). "VEGF, Flt-1 and KDR expression was present in the cytoplasm and vessels of the ovarian cancer tissues, exhibited as focal or diffuse expression." (PMID 23946799, 2013). "The present study aimed to investigate the correlation between the expression of vascular endothelial growth factor (VEGF) and its receptors, the Flt-1 and KDR proteins, with clinical pathology and microvessel density (MVD) in ovarian cancer tissue." (PMID 23946799, 2013). "Similarly, treatment with fucoidan repressed the mRNA expression of angiogenesis related genes including VEGFA, VEGFB, VEGFC, VEGFD, FLT-1, FLT-4, and KDR in the ovarian cancer cells." (PMID 31936539, 2020). "Confirming the results of our previous studies in a co-culture model with synthesized Ovcar-3 cells we found a significant (p < 0.05) decrease of claudin 5 in HUVEC co-cultured with our human ovarian cancer cells, which was prevented by simultaneous treatment with the VEGF-inhibitor Flt1-Fc." (PMID 26868378, 2016). "In addition, for VE-cadherin a comparable significant (p < 0.05) decrease in HUVEC co-cultured with our human ovarian cancer cells was detected, which was prevented by simultaneous treatment with the VEGF-inhibitor Flt1-Fc." (PMID 26868378, 2016).
prostate carcinoma (19 papers, 2002 to 2025). A carcinoma that arises from epithelial cells of the prostate gland. "Of note, prostate cancer metastases from the Dream Team cohort also displayed relatively high correlation coefficients of FAP with FLT1 and KDR—thereby potentially mirroring the importance of angiogenesis in high-risk prostate cancer, as previously reported." (PMID 36672341, 2023). "They showed promising data where EV proteins such as CD10 and Flt1 could discriminate enlarged yet benign prostatic hyperplasia from genuine prostate cancer." (PMID 31162490, 2018). "SKAP1 (rs6504145) in Han Chinese populations was detected to affect prostate cancer specific mortality in advanced prostate cancer populations, and variation in FBXO32 (rs7830622) and FLT1 (rs9508016) appeared to affect all-cause mortality in advanced prostate cancer." (PMID 22956944, 2012). "In agreement with our results, Flt-1 and KDR (both receptors for VEGF) have been identified on malignant cells from human CNS, breast, prostate cancer and in cell lines derived from these tumors." (PMID 17877803, 2007). "The concomitant expression of PLGF, HIF-1α, and VEGFR1 (FLT1 gene) was significantly higher in metastasis compared to non-metastatic prostate cancers (p = 1.71 × 10−1)." (PMID 39457506, 2024). "In prostate cancer VEGF promotes angiogenesis by binding VEGF-R2 (Flk-1) on the vascular endothelial lining to promote proliferation and vascular permeability, then organization of nascent capillary tubes into the tumor microenvironment via VEGF-R1 (Flt-1)." (PMID 29562686, 2018).
Sepsis (17 papers, 2011 to 2025). Sepsis is defined as life-threatening organ dysfunction caused by a dysregulated host response to infection. "In this systematic review, we found that the FER gene (rs4957796) was significantly associated with 28-day survival in patients with sepsis due to pneumonia and the FLT1 gene (rs9508032) with sepsis-associated ARDS." (PMID 40168842, 2025). "While IL-6, PIGF, and CRP were also significantly elevated in post-Sepsis patients compared to controls, the observed differences in TNFα, Tie-2, Flt-1, IL-7 and bFGF were unique to the post-COVID group." (PMID 36844209, 2023). "An SNP in FLT1 (rs9513106) was associated with reduced susceptibility to ARDS in a cohort study involving adults of Spanish and Western European descent with sepsis." (PMID 35913450, 2022). "The different kinetics of s-Flt-1 between sepsis and septic shock may result from the most prominent damage of the vasculature in shock." (PMID 34871241, 2021). "Sepsis-induced alteration in angiogenic gene expression can be time-dependent and therefore it is possible that either downregulation or upregulation of Angpt2, Vagfα, and Flt1 was more robust at other time points." (PMID 25959381, 2015). "PCT and s-Flt-1 baseline levels were higher in sepsis and septic shock compared to non-sepsis; this was not the case for PlGF." (PMID 34871241, 2021). "Regarding the secondary endpoint of sepsis diagnosis, PCT, and s-Flt-1 on the first day were higher in patients with severe sepsis/septic shock compared to infection/SIRS; PlGF could not discriminate between infection/SIRS and severe sepsis/septic shock." (PMID 34871241, 2021). "Importantly, we also showed for the first time that persistent changes in Tie-2, Flt-1, bFGF, IL-7, and TNFα were uniquely seen in patients following recovery following COVID-19, but not in patients recovering from severe sepsis." (PMID 36844209, 2023).
pancreatic cancer (16 papers, 2010 to 2025). "Also, it has been reported that FLT-1 is variably expressed in pancreatic cancer, and correlates significantly with disease stage." (PMID 29697368, 2018). "Another example is vascular endothelial growth factor receptor-1 (VEGFR-1, Flt-1), whose activation by VEGF-A or VEGF-B leads to increased migration, invasion, and EMT in the pancreatic carcinoma cell line L3.6pl." (PMID 24281218, 2010).
osteosarcoma (15 papers, 2016 to 2025). A usually aggressive malignant bone-forming mesenchymal neoplasm, predominantly affecting adolescents and young adults. "This study is the first one to show significant associations between RFS and OS and two variants in the FLT1 gene in patients with localized osteosarcoma." (PMID 41471344, 2025). "Validation in an independent cohort and further functional studies are required to support the FLT1 variants rs7993418 and rs9582036 as prognostic biomarkers in osteosarcoma disease." (PMID 41471344, 2025). "Current treatment strategies aimed at improving outcomes for osteosarcoma patients may benefit from the identification of new biomarkers, such as these FLT1 rs7993418 and rs9582036 variants." (PMID 41471344, 2025). "In conclusion, FLT1 rs7993418 and rs9582036 variants may be prognostic biomarkers of survival in high-grade localized osteosarcoma treated with chemotherapy." (PMID 41471344, 2025). "The aim of this study was to evaluate the prognostic value of germline polymorphisms in key genes of the VEGF signaling pathway (VEGFA, FLT1 and KDR) in a prospective multicenter cohort of patients with localized high-grade osteosarcoma treated with the GEIS-33 protocol." (PMID 41471344, 2025).
Stroke (14 papers, 2009 to 2025). Sudden impairment of blood flow to a part of the brain due to occlusion or rupture of an artery to the brain. "Candesartan treated animals showed a visual increase in phospho-flt-1 (activation of VEGFR1) expression in the stroke hemisphere and increased phospho-flk-1(activation of VEGFR 2) expression in the nonstroke hemisphere, but neither achieved statistical significance." (PMID 21912702, 2011). "Using CD105 and Flt-1 as discriminating markers of microvessel activation, we aimed to identify the molecular fingerprint responsible for neovessel activation and revascularization following stroke." (PMID 19292924, 2009). "In stroke-prone spontaneously hypertensive rats were found downregulation of VEGF, VEGFR-1 (Flt-1), and VEGFR-2 (Flk-1) receptors, endothelial nitric oxide synthase and the phosphorylated Akt in frontal cortex." (PMID 28751869, 2017). "Here, we have isolated active (CD105/Flt-1 positive) and inactive (CD105/Flt-1 minus (n=5) micro-vessel rich-regions from stroke-affected and contralateral tissue of patients using laser-capture micro-dissection." (PMID 19292924, 2009). "VEGFR1 (flt-1) was significantly higher in the stroke hemisphere when compared to the nonstroke side (P = 0.0036) for all treatment groups." (PMID 21912702, 2011).
angiosarcoma (13 papers, 2009 to 2025). A malignant tumor arising from the endothelial cells of the blood vessels. "GSEA highlighted unique differences between hemangiosarcomas segregated by breed: for example, Flt-1/VEGFR1 was exclusively enriched in GSEA pathways separated according to breed." (PMID 19461996, 2009). "In about 10% of angiosarcomas, mutations in the VEGFR2 or VEGFR3 can be detected, and gene expression profiling shows upregulation of TIE1, VEGFR2, SNRK, TEK (TIE2) and FLT1 (VEGFR1), all playing a role in angiogenesis." (PMID 26474454, 2015). "Cytogenetically, the expression of FLT1 and AKT3 in the angiosarcomas patients was up-regulated." (PMID 33509230, 2021).